CTLA4 (cytotoxic T-lymphocyte associated protein 4)
Diseases named in the same sentence as CTLA4 in open-access papers (continued):
Sharing a sentence is not in itself a finding about the gene and the disease.
tumor (continued). "BTKi augments CART function via TME modulation, including reduced PD-1 and CTLA-4 expression, inhibition of Tregs, downregulation of B-cell chemokines and disruption of tumor cell adhesion/homing." (PMID 36010965, 2022). "The inflammatory context and the cell type where anti-CTLA-4/anti-PD-1-mediated NLRP3 activation takes place to instruct anti-tumor immunity remain to be determined." (PMID 36032139, 2022). "Tumor immunotherapy, such as PD-1/PD-L1, CTLA-4 antibody therapy and CAR-T/CAR-NK immune cell therapy, is based on the activation of immune cells, especially T cells, which can kill cancer cells." (PMID 35892755, 2022). "Results from our present work revealed that the predictive roles of LOXs expression in tumor immunotherapy were also confirmed in two immunotherapy cohorts including IMvigor 210 (anti-PD-L1 therapy) and Van Allen 2015 (anti-CTLA4 therapy)." (PMID 36160460, 2022). "In this study, a combination of whole-animal in vivo imaging and ex vivo imaging of recovered LNs provided direct evidence that a peri-tumor injection of hydrogel-encapsulated anti-CTLA-4 creates a local drug reservoir that targets mAb delivery to TDLN." (PMID 35621582, 2022). "One class of ICi, anti-cytotoxic T-lymphocyte-associated protein 4 (CTLA-4) antibodies, prevent CTLA-4 on T-cells from interacting with inhibitory signals on antigen-presenting cells, thereby increasing anti-tumor T-cell response." (PMID 35513054, 2022). "The use of CTLA-4 and PD-1 or its ligand PD-L1 inhibitor can relieve the immunosuppressive state and restore the anti-tumor immune response." (PMID 35300113, 2022). "Two recent phase II trials (DART and CA209-538) evaluated the anti-tumor activity of dual anti-CTLA-4 and anti-PD-1 blockade in high-grade neuroendocrine neoplasms." (PMID 35681675, 2022). "Tumors treated with sitagliptin, in addition to anti-PD1/anti-CTLA4 antibodies, also demonstrated significantly lower tumor volume compared to controls." (PMID 35954493, 2022). "Fecal microbial transplantation from humans to mice confirmed that B. fragilis and B. thetaiotaomicron promote tumor CTLA-4 blockade reactivity by promoting the IL-12-dependent TH1 immune response." (PMID 36358736, 2022). "The anti-PD-L1 antibody combined with regorafenib plus chidamide-k30 regimen more effectively inhibited tumor growth than the anti-CTLA-4 or anti-PD-1 antibody combination regimens." (PMID 36142591, 2022). "Monoclonal antibodies antagonizing CTLA-4, PD-1, and other immune checkpoints have been developed to counteract such tumor evasion strategies and stimulate anti-tumor immune responses." (PMID 35692394, 2022). "Immune checkpoint blockers, including antibodies against cytotoxic T lymphocyte antigen-4(CTLA4), programmed cell death protein 1(PD-1) and its ligand PD-L1, enhance T cell anti-tumor immune function." (PMID 36324573, 2022). "Many checkpoint proteins exist, including the cytotoxic T-lymphocyte-associated protein 4 (CTLA-4) located on APC surfaces, the programmed cell death protein-1 (PD-1) located on T-cells and the programmed death ligand-1 (PD-L1) located on tumor cells." (PMID 35406412, 2022). "Given the appropriate conditions in the TME, it suggests that anti-CTLA-4 can promote anti-tumor immune responses by increasing Th1-like Tregs that positively correlate with granzyme B and/or IFN-γ producing CD8+ TILs." (PMID 35326731, 2022). "For example, focused ultrasound was used to trigger a temperature-dependent operon that induced the expression of anti-CTLA-4 and anti-PD-L1 by engineered tumor-homing probiotic E. coli Nissle 1917." (PMID 36672796, 2022). "Immune checkpoints, most notably cytotoxic T-lymphocyte-associated protein 4 (CTLA-4) and programmed cell death protein 1 (PD-1), inhibit effector T lymphocytes to limit the anti-tumor autoimmune response." (PMID 35243562, 2022).
tumor (continued). "Some scientists found that drugs directly against either PD1 or PD-L1 had lower adverse effects than CTLA4 inhibitors for their direct action in tumor microenvironment." (PMID 35581573, 2022). "Further, the genetic deletion of SLC7A11 in various preclinical tumor models acts synergistically with immune checkpoint immunotherapeutic agents, such as anti-CTLA4, to suppress tumor growth." (PMID 35065965, 2022). "Checkpoint inhibitors block the inhibitory signaling when T-cells interact with tumor cells, by targeting PD-1 and/or CTLA-4." (PMID 36145510, 2022). "The efficacy of anti-PD-1 & anti-CTLA blockade is thought to largely depend on the disinhibition of tumor-specific T cell populations controlled by the PD-1 and CTLA4 immune checkpoints for enhanced proliferation and tumor cytotoxicity." (PMID 36503532, 2022). "Compared to systemic dosing, peri-tumor injection of hydrogel-encapsulated anti-CTLA-4/DyLight 800 resulted in preferential labeling of TDLN." (PMID 35621582, 2022). "Treating the FAP+ CAF-depleted mice with ICIs targeting PD-L1/CTLA-4 dramatically reduced tumor volumes." (PMID 36627901, 2022). "The PTEN/PI3K pathways are responsible for HIF-1-mediated upregulation of CTLA-4, PD-L1, and HLA-G checkpoint molecules in several different mice and human tumor cell lines." (PMID 35158804, 2022). "Immune checkpoint inhibitors, such as PD-1/PD-L1 and CTLA-4 inhibitors, increase immune-mediated destruction of tumor cells by interrupting tumor inhibition of T-cell-mediated apoptosis." (PMID 35954441, 2022). "The TMEscore-low subtype showed overexpression of PD-1, CTLA4, and associations of other markers of sensitivity to immunotherapy, including TMB, immunophenoscore (IPS) analysis, and tumor immune dysfunction and exclusion (TIDE) algorithm." (PMID 35677561, 2022). "Apart from T-cell expression, the upregulation of co-inhibitory molecules, such as PD-1/CTLA4 and others, on APCs plays a crucial role in tumor immune avoidance." (PMID 35455289, 2022). "LC4 peptide has been demonstrated to effectively block CTLA-4 /B7 protein interactions and has good anti-tumour effect in vitro and in vivo." (PMID 36195696, 2022). "CTLA4 antibody (ipilimumab) can restore T cells priming and activation by tumor antigens and promote antitumor T cell response." (PMID 36081514, 2022). "Leflunomide-treated tumors that inhibit a key enzyme for ab initio synthesis of pyrimidine exhibited reduced CTLA-4+ T cells, suggesting reduced intra-tumor T cell depletion and possibly increased anti-tumor immunity." (PMID 36524129, 2022). "Ipilimumab binds to CTLA-4 on T cells, which enhances the anti-tumour immune response, whereas monoclonal antibodies such as Pembrolizumab and Nivolumab exert anti-tumour immune response by blocking PD-1 and PD-L1 signalling." (PMID 35993275, 2022). "Consistently increased local and distant responses with increased frequency of complete tumor regression were demonstrated in murine models of poorly immunogenic breast cancer when multi-fraction RT was combined with an anti-CTLA-4 antibody." (PMID 35804917, 2022). "These antigens are the immune checkpoints: PD-1, PD-L1, as well as CTLA-4, which suppress anti-tumor immunity and apoptosis, leading to unrestricted replication." (PMID 35629333, 2022). "We also computed survival models testing the relationship between OX40L, CTLA4, and CD11c protein expression in both tumor and tumor-adjacent stroma samples with time to biochemical relapse." (PMID 36230846, 2022). "In this regard, targeting CTLA-4 and PD-1 on the activated T cells’ surface leads to the immunologic tolerance of cancer cells in the tumor setting." (PMID 36276117, 2022). "Strikingly, the application of RBMS1-depletion with CTLA4 blockade demonstrated a significant improvement in tumor burden and survival rate of mice." (PMID 35538152, 2022).
tumor (continued). "This study showed that MWA combined with anti-PD-1/anti-CTLA-4 increased the survival time and protected the mice from tumor recurrence, through the increase of Th1-type cytokines and intratumoral infiltration of Th1 cell response." (PMID 35884392, 2022). "The discovery of immune checkpoints, such as PD-1, CTLA-4, LAG-3, and TIM-3, has shifted the cancer treatment paradigm by targeting cancer itself to modulate a tumor-associated immune response." (PMID 36077619, 2022). "Some studies used anti‐PD‐1 and anti‐CTLA4 antibodies to treat residual tumor after RFA‐mediated tumor size reduction." (PMID 36002305, 2022). "This compound has been shown to augment the activity of ICIs targeting either PD-1, PD-L1 or CTLA-4, and significantly increase tumor regression." (PMID 35037899, 2022). "Mixed model ANOVA analysis showed that the addition of tretinoin to αCTLA4 significantly delayed tumour growth compared both anti-CTLA-4 monotherapy (p=0.014) and tretinoin monotherapy (p<0.001)." (PMID 35402250, 2022). "Following production of subcutaneous tumors in syngeneic hosts, mice were treated with anti-CTLA4 therapy and monitored for tumor response and changes in immune infiltration." (PMID 36344707, 2022). "According to existing studies, anti-CTLA-4 treatment will promote the depletion of Treg in the tumor microenvironment, indicating that CTLA-4 contributes to Tregs' activation." (PMID 34998385, 2022). "Immune checkpoint inhibitors block binding of tolerogenic ligands CTLA-4 and PD-1 to their cognate receptors, and therefore promote the activity of host anti-tumor T cells silenced by tumor activation of these pathways." (PMID 36077755, 2022). "In tumor islets where T cells are in contact with cancer cells, PD-1 and CTLA-4 likely act by interrupting TCR-mediated stop signals." (PMID 35681548, 2022). "These TILs are frequently suppressed in the TME by immune checkpoint molecules such as CTLA-4 and PD-1/PD-L1, but can be reactivated following checkpoint blockade and thus able to induce tumor regression." (PMID 35432319, 2022). "For instance, in a mouse model of PDAC, the use of an anti-CSF1-R antibody in combination with antagonists of PD-1 and CTLA-4 enhanced antigen presentation and productive anti-tumor T cell responses leading to tumor regressions." (PMID 35163420, 2022). "The function of CTLA4 in tumorigenesis and tumor immunity has been widely investigated, and some CTLA-4 inhibitors were clinically actionable." (PMID 35237510, 2022). "As PD-1, CTLA-4 is broadly engaged during tumour immune evasion to suppress CD4+ effector T-cells and boost Treg activity." (PMID 36011012, 2022). "The anti-PD-1 and anti-PDL-1 antibodies exhibit synergistic activity in preventing CTLA-4-mediated downregulation, reducing T-cell apoptosis and increasing the net activity of activated T-cells against tumor cells." (PMID 35160275, 2022). "The understanding that tumor cells utilize co-inhibitory signals to evade immune clearance drove the effort to create anti-PD-1 and Anti-CTLA4 therapies." (PMID 35455289, 2022). "Several investigations have demonstrated that RIG‐I agonists greatly induce synergistic anti‐tumour effects when combined with immune checkpoint inhibitors, such as anti‐CTLA‐4 and anti‐PD‐1 antibodies." (PMID 35430766, 2022). "Taken together, our data suggest that LS diet inhibits the anti-CTLA4 mAb-induced irAE response while retaining its anti-tumor efficacy." (PMID 35741331, 2022). "CTLA-4 was found to be expressed on TILs within the epithelial component of the tumor, the surrounding tumor stroma and the invasive front of the tumor." (PMID 36072957, 2022). "Overall, these findings illustrate that CTLA-4-silenced tumor lysate-loaded DCs are a very attractive option for upgrading the effectiveness of DC vaccines in cancer immunotherapies." (PMID 35979362, 2022).
tumor (continued). "Combining anti-IDO1 antibodies with anti-CTLA-4 and anti-PD-L1 antibodies decreases the presence of tumor-infiltrating Tregs and provides a durable survival benefit." (PMID 35203636, 2022). "Pembrolizumab and nivolumab (targeting PD-1) and ipilimumab (targeting CTLA-4) have been applied in GC treatment with encouraging anti-tumor results." (PMID 35465325, 2022). "Adding the CTLA-4 to the PD-1/PD-L1 blockade can enhance the immune response against the tumour, blocking a second immune checkpoint exploited by tumour cells to evade immune surveillance." (PMID 36230538, 2022). "As for the two classical immune checkpoints, some studies suggested that conjoint immunotherapy, including anti-PD-1 and anti-CTLA-4, would exhibit superior anti-tumor responses compared with single-agent therapy." (PMID 35978433, 2022). "Regarding immunotherapy, ICIs targeted CTLA4, PD-1, and its ligand PD-L1 and worked primarily by triggering an efficient cytotoxic T cell-driven anti-tumor immune response." (PMID 36467089, 2022). "Our results also indicate that a higher coexpression of CTLA-4, PD-L1, and ICOS in normal lung tissues, presumed to induce an immune tolerance to tumor neoantigens, was associated with a shorter DFS after curative-intent surgery." (PMID 36108261, 2022). "PD-1 and CTLA-4 antagonists have revolutionized the treatment of multiple tumor types by increasing the quality of T cell priming by DCs, improving expansion of stem-like T cells, and ‘reviving’ exhausted tumor antigen-specific T cell responses." (PMID 35379805, 2022). "The nature of PD-1/PD-L1, CTLA-4 is a ligand or receptor for the interaction between tumor cells and immune cells, which serves as immunomodulatory role." (PMID 35159131, 2022). "Irrespective of inhibition of the costimulation, CTLA-4 inhibitors can also attenuate regulatory T (Treg) cell recruitment into tumor tissue due to the high expression of CTLA-4 on the surface of Treg." (PMID 34980128, 2022). "The discovery of immune checkpoint molecules and the elucidation of their functions have provided new targets and therapeutic methods for tumor therapy, such as CTLA-4, PD-1, Lag-3 and Tim-3." (PMID 36439090, 2022). "More importantly, the combination of anti-CTLA-4 and anti-PD-1/PD-L1 showed stronger anti-tumour activity than monotherapy." (PMID 36110204, 2022). "Tumor cells exploit this mechanism by also expressing PD-1 or CTLA-4 to generate an immune-tolerant environment." (PMID 35163401, 2022). "Checkpoints are inhibitors of anti-tumor T cells; CTLA-4 prevents T cell activation while PD-1 functionally inactivates TCR and CD28 signaling, dampening T cell effector function." (PMID 35474500, 2022). "In fact, the modulation of TME by propranolol increases tumor T cell infiltration and the efficacy of anti-CTLA-4 treatment." (PMID 36713558, 2022). "Immune checkpoint molecules, including PD-1 and CTLA-4, play crucial roles in tumor immune tolerance, which is the main reason for the poor clinical outcomes of immunotherapy." (PMID 36230955, 2022). "The results showed that CTLA-4 mAb treatment significantly decreased the tumor volume compared with the IgG2b group." (PMID 36050478, 2022). "Ipilimumab, anti-CTLA-4, was the first ICPi to display high anti-tumor activity in patients with metastatic melanoma, and it was the first FDA approved by 2011." (PMID 35327411, 2022). "PD-1, which binds to PD-L1, also known as CD274, or to PD-L2/CD273, is a peripheral immune checkpoint of immune, tumor, and stromal cells, whereas CTLA-4 binds to CD80/CD86, also known as B7-1/B7-2 co-stimulatory receptors, on antigen-presenting cells (APCs)." (PMID 35159208, 2022). "In the subcutaneous setting with Panc02 tumors, anti-PD-1/anti-CTLA-4 treatment resulted in a synergic effect, with Slc4a4 deletion leading to tumor regression or to a static disease, overall offering an increased survival." (PMID 36522548, 2022).
tumor (continued). "In our previous publication, therapeutic CTLA4-PD-L1 DNA cancer vaccines can reduce iCCA tumor growth in a rat thioacetamide (TAA)-induced iCCA model." (PMID 36341387, 2022). "We observed astriking difference in the response to anti-PD-1 or anti-CTLA-4 in subcutaneousversus orthotopic tumours, as previously demonstrated for PD-1/PD-L1 blockade." (PMID 35930804, 2022). "It was discovered that patients with high m6A scores had longer survival, lower tumor mutation loads, and low PD-L1/PDCD1/CTLA4/TAG3 expression level." (PMID 35419413, 2022). "Tregs play an important role in maintaining immune homeostasis, but they also contribute to tumor immune evasion through competitively binding with receptors on T cells including PD-L1 and CTLA4." (PMID 35676688, 2022). "Studies have also demonstrated that CTLA-4 is constitutively expressed on tumor cell lines at various degrees of intensity and can trigger apoptosis of CTLA-4-expressing tumor cells after interaction with soluble CD80 or CD86 recombinant ligands." (PMID 36104728, 2022). "They suggest that Treg depletion and tumor rejection by anti-CTLA-4 is instead Fc-receptor mediated." (PMID 35326731, 2022). "Anti-CTLA-4/PD-1 treatment under this schedule induced a partial improvement in the tumor progression, similar to the observed with AS1411-SMG1 AsiC treatment." (PMID 35991316, 2022). "CTLA-4 and PDCD-1 are important immune checkpoint proteins that are associated with tumor immune escape." (PMID 35769911, 2022). "Conversely, anti-CTLA-4 constructs with enhanced FcR binding affinity exhibit enhanced anti-tumor activity and Treg depletion." (PMID 35326731, 2022). "Strategies that aim to target intra-tumoral Tregs preferentially with anti-CTLA-4 can enhance anti-tumor immune responses while minimizing toxicity." (PMID 35326731, 2022). "Leukocytes, including T cells, especially killer cells, B cells, and mature B cells as well as CTLA-4 and PD-1 expressing cells showed higher expression in lymph node metastatic tumor regions." (PMID 35456394, 2022). "Currently, there are three commonly used indicators for predicting the effectiveness of immunotherapy, that is, tumor mutation burden (TMB), microsatellite instability (MSI), and immune inhibitory genes (e.g., PD1/PD‐L1, CTLA‐4)." (PMID 35986392, 2022). "As in other tumor subtypes, we reviewed the inhibition of the CTLA4 pathway with single agents and found a unique trial with ipilimumab." (PMID 36497437, 2022). "Given that B7-1 and B7-2 are only expressed on APCs, CTLA4 blockade is thought to mainly occur in tumor-draining lymph nodes, where APCs present tumor antigens to prime naive T cells." (PMID 35493449, 2022). "Both CTLA-4 and PD-1/PD-L1 can block tumor infiltrating lymphocytes (TILs) and promote tumor growth and progression." (PMID 35158750, 2022). "The presence of activated cytotoxic CD8+ T cells are important for initiating and mediating a successful response to CTLA-4 and PD-1/PD-L1 checkpoint blockade treatments 77-79 and has been shown to be of prognostic value for tumor response in patients." (PMID 35223381, 2022). "Taken together, there are strong preclinical data suggesting that intratumoral Treg depletion is a mode-of-action for generating anti-tumor immunity following anti-CTLA-4 therapy." (PMID 35237846, 2022). "For the tumor cells, there were 7 (54%, PD-L1), 0 (0%, PD-1), 1 (8%, CTLA-4), 3 (23%, IDO) cases showed positive IHCs staining." (PMID 36104728, 2022). "While CTLA-4 regulates T-cell activity at the priming phase, PD-1 mainly acts to limit T-cell activity in peripheral tissues at later stages of tumor growth." (PMID 36648843, 2022). "Mice bearingsubcutaneous KPAR tumours were treated with anti-PD-1, anti-CTLA-4 or acombination of both." (PMID 35930804, 2022). "Through the inhibition of the CTLA4 via ipilimumab and the application of adoptive cellular immunotherapy with tumor-infiltrated lymphocytes, it enhanced the anti-tumor effects of T cells." (PMID 36353107, 2022).